IL1B (interleukin 1 beta)
Diseases named in the same sentence as IL1B in open-access papers (continued):
Sharing a sentence is not in itself a finding about the gene and the disease.
infection (continued). "Treatment of caspase-1 KO mice with IL-1β microparticles significantly reduced S. aureus burden in the brain and galea compared to empty microparticles, confirming the critical role of IL-1β in limiting S. aureus outgrowth during craniotomy infection." (PMID 32290861, 2020). "In accordance with other studies, BALFs from patients with severe/critical infection showed much higher levels of IL-8, IL-6, and IL-1β expression than those from patients with moderate disease." (PMID 33062077, 2020). "IL1β transcription was the highest on days 12 and 16 post-infection in the challenged turtles at both temperatures." (PMID 33119713, 2020). "The results showed that the concentrations of IL-8 and IL-1β in the supernatant of Caco-2 cells infected with ΔvbrK were significantly higher than those observed after infection with the WT strain." (PMID 33188170, 2020). "Compared to WT animals, both TNF-α and IL-1β increased in the lungs of Il22−/− mice at the 7th day of infection, correlating with increased lung inflammation at the same time point." (PMID 32517114, 2020). "NLRP3 deficiency mice are more susceptibility to HSV-1 infection, exhibit early onset of death upon infection, represses IL-1β secretion, and elicits robust inflammatory responses in the tissues." (PMID 32187211, 2020). "IL-1β concentrations remained low for saline control and 5448 infected mice but were significantly increased at 24 h during 5448AP infection (p<0.0001)." (PMID 33585270, 2020). "We observed down regulation of IL-22 and IL-10 in spleen of salmon at chalimus stage of infection and an increase in IL-1β, TNF-α and IL-8 at subsequent pre-adult stage in group 2." (PMID 33006991, 2020). "We observed that Ifi44−/−/Ifi44L−/− mice infected with RSV had higher levels of viral RNA present in their lungs at the peak of infection, along with decreased expression of the proinflammatory factor interleukin-1β (IL-1β)." (PMID 32611756, 2020). "As a result, the expressions of NF-κB, IL-1β, and IL-6 in SEECs were increased after infection with E. coli, and there was a dose-dependent effect when the MOI was beneath 5:1." (PMID 32426380, 2020). "Reduced IL-1β and IL-6 levels were detected in the infected tracheal organ cultures, relative to infected trachea, at 24 h post infection, which is in agreement with the reduction in inflammatory response noted in the chicken PCLS during early culture." (PMID 31924278, 2020). "Complementation of VPRH restored all of the inflammasome-mediated phenotypes upon BMDM infection, including rapid cell death, IL-1β secretion, as well as cleavage of caspase-1, maturation of IL-1β, and cleavage of GSDMD." (PMID 32013758, 2020). "Bmal1 deficiency in bone marrow-derived macrophages leads to increased IL-1β expression and increases polymicrobial infection in mice." (PMID 33363534, 2020). "Taken together, these data suggest that not only P2X7R but also P2Y2R, a G-protein-coupled receptor, is involved in the activation of IL-1β production/release in immune cells during infection with L. amazonensis." (PMID 33061823, 2020). "Another study involving 20 consecutive SARS patients admitted to a Hong Kong hospital identified significantly elevated levels of IL-1β within the first 12, 7 and 5 days following onset of infection." (PMID 32256705, 2020). "Following infection with Brucella abortus vaccine strain RB51, mice treated with 4μ8C which selectively inhibits IRE1α RNase activity show less serum IL-1β and increased susceptibility to RB51, as reflected by increased bacterial burden in the spleen." (PMID 32423023, 2020). "To further study the effect of PKK depletion on lung inflammation after infection, we measured the levels of cytokines (TNFα, IL‐1β, IL‐6) and chemokines (CXCL1, CXCL2) in lung homogenates." (PMID 31595971, 2020). "In contrast, activation of the NLRP3 inflammasome and production of IL-1β led to an increase in the pathology of murine infection by L. braziliensis." (PMID 33192178, 2020).
infection (continued). "For IL-1β and TNF-α, we found significantly increased levels in spinal cord tissue in the infected group ten weeks after infection, and daily artesunate treatment, started two weeks after the infection, significantly reduced the levels of IL-1β and TNF-α." (PMID 32230725, 2020). "Roles of IL-1β in mediating infection-induced acute sickness behaviors, the pathophysiological interactions between brain and immune systems, are well known." (PMID 32070376, 2020). "In order to improve our knowledge of the interaction between the immune system and S. haemolyticus during the infection, we investigated the expression of IL1β, IL4, IL17, IFNγ, TNFα, TGFβ and IL10 by PBMCs infected withS." (PMID 32799619, 2020). "IL‐1β and TNFα are two major pro‐inflammatory cytokines generated in response to infection and contribute to tissue injury during disease." (PMID 31520551, 2020). "Either IAL alone or in combination with penicillinG resulted in a significant decrease in TNF-α, IL-1β and IL-6 levels in the fluid at 36 h post infection." (PMID 32110983, 2020). "Multiple studies show that IL-1β is typically activated in macrophages after inflammasome sensing of infection or danger, leading to caspase-1 processing of IL-1β and its release." (PMID 33391283, 2020). "Immunological investigation of the ZF strain exhibits susceptibility to infection, T-lymphocytopenia, production of immunoglobulins and nitric oxide, and increased expression of tumor necrosis factor-α (TNF-α) and interleukin-1 beta (IL-1β)." (PMID 33287318, 2020). "Microparticles contain chemokines (e.g., RANTES) and cytokines (e.g., IL-1β) and thus are able to trigger inflammation distant from the site of infection." (PMID 33123129, 2020). "In paw tissue from infected mice after infection, we found a significantly increased level of the principal proinflammatory cytokines IL-1β, IL-6, and TNF-α, while treatment with artesunate significantly reduced the levels of these cytokines." (PMID 32230725, 2020). "For the case of Toxoplasma, inflammasome components NLRP1 and NLRP3 respond to infection resulting in IL-1β and IL-18 release, in turn promoting resistance to infection." (PMID 33505924, 2020). "Mice infected with IC-proficient rSARS-CoV E developed pulmonary edema, lung damage, and succumbed to the infection due to significantly increased levels of inflammatory cytokines IL-1β, IL-6, and TNF-α." (PMID 33013759, 2020). "The coefficients of variation show that also after FIPV infection all cytokines except IL-1β were transcribed with high inter-individual and inter-test variations." (PMID 33121170, 2020). "IL-1β levels remained constant during the 14 days following Ad14 infection; however, infection with Ad14p1 resulted in a further induction of IL-1β at day 3 p.i. that returned to a level comparable to that induced by Ad14 infection by day 5 post infection." (PMID 32486177, 2020). "The body temperatures of the two chickens in the anti-IL-1β-treated group gradually increased after infection, peaked on the 5th day, rapidly decreased, and then slowly returned to normal." (PMID 32293543, 2020). "The inflammasome controls infection through activation of caspase-1 leading to either IL-1β dependent inflammation, or pyroptotic cell death in infected cells." (PMID 32013758, 2020). "The Salmonella-challenged treatment (T2) follows the previously documented studies: IL-6 and IL-1β are highly upregulated on day 2 and dramatically reduced by day 4 post-infection." (PMID 33260977, 2020). "MIPs are crucial for immune responses towards infection and inflammation and are produced by macrophages and monocytes, and stimulated by proinflammatory cytokines such as IL-1β." (PMID 33046133, 2020). "Activation of the NLRP3 inflammasome and subsequent release of IL-1β is also critical during control of infection with West Nile Virus (WNV)." (PMID 33584721, 2020).
infection (continued). "PAF mediates IL-1β-induced chemotaxis of natural killer cells and neutrophilsand can induce the migration of neutrophils to infection sites." (PMID 32308652, 2020). "Incubation with GAS induced IL-1β release from neutrophils at 180 and 360 min, with significantly greater release during 5448AP infection compared to 5448 at 180 and 360 min (p<0.05, p<0.0001)." (PMID 33585270, 2020). "Turtles challenged with FV3 were observed with measurable and significantly different hematologic (heterophils, lymphocytes, HL ratio) findings and cytokine (IL1β) quantities at two different environmental temperatures indicative of infection." (PMID 33119713, 2020). "In children aged 3 to 17 years with H1N1 influenza virus infection and severe clinical manifestations of the infection, IL-1β and IL-6 plasma levels were significantly upregulated when compared to children with H1N1 and mild symptoms." (PMID 33542685, 2020). "We also established a role for IL-1β during craniotomy infection by the ability of exogenous IL-1β delivery to prevent heightened bacterial burden in caspase-1 KO mice." (PMID 32290861, 2020). "We demonstrated that Rv0341 significantly induced early expression of IL-1β at 6 h of post-infection of the THP-1 macrophage." (PMID 32521796, 2020). "The inflammatory cytokines IL-1β and IL-6 as well as TNFα showed similar trends of increase in both infection protocols, albeit with more prominent increases of TNFα under SARS-CoV-2 infection." (PMID 33163005, 2020). "The presence of a viral IL-1β decoy was shown to reduce virulence and febrile reactions to infection, and deletion of the immune evasion factor was shown to enhance Th1-mediated immunogenicity in a vaccinia virus mouse model." (PMID 31833037, 2020). "IL-1β mediated chemokine (CXCL1/2) release is necessary for suppressing infection via neutrophil activation, similarly IL-8 mediated CXCL2 release simultaneously triggers neutrophil activation and proliferation." (PMID 33634060, 2020). "First, in order to validate the model within our experimental conditions, we ran a set of experiments using BMDMs exposed to N. caninum to determine the kinetics of IL-1β production in macrophages during infection." (PMID 32523898, 2020). "For example, infection with Salmonella in mice induces the processing of pro-interleukin 1β (pro-IL1β)." (PMID 33324424, 2020). "The pleiotropic cytokine IL-1β, a master regulator of inflammation, is essential for controlling infection, maintaining host homeostasis, and supporting adaptive immunity." (PMID 32983094, 2020). "The protein induces expression of pro-IL-1β, CXCL2, and CCL2, leading to the activation of primary neutrophils and further recruitment of macrophages, which are highly susceptible to infection." (PMID 32850501, 2020). "Detection of the processed forms of IL-1β and caspase-1 was highly delayed and remained undetectable until 12 h post infection." (PMID 33424869, 2020). "Supplementation of IL-1β KO mice with recombinant IL-1β restored the mice’s ability to control infection and clear S. aureus." (PMID 33542723, 2020). "IL-1β and IL-1α increase acute-phase signaling, homing of immune cells to the site of primary infection and epithelial cell activation, both inducing the production of many other cytokines." (PMID 32397174, 2020). "Pro-inflammatory cytokines like IL-1α, IL-1β, IL-6, and IL-8 have been noted for their roles in early infection response, producing a warning signal of pathogen invasion, and this response was present in septic TKR tissues." (PMID 32867801, 2020). "Taken together, our results show that Casp1/11 and Asc are required for IL-1β processing following infection with M. tuberculosis clinical isolates." (PMID 32111888, 2020). "To confirm an increased pro-inflammatory status of the human lung epithelial cells upon super-infection, we analyzed the mRNA expression of different representative pro-inflammatory cytokines and chemokines (IL-6, IL-8, TNFα, IL-1β, and IFN-γ) in detail." (PMID 33333815, 2020).
infection (continued). "Seven cytokines showed infection-dependent increases in localized tissues: IL-1α, IL-1β, IL-6, IL-8, MCP-1, MIP-1α, and MIP-1β (p < 0.05)." (PMID 32867801, 2020). "Infection induced IL-1α and IL-1β production in both phenotypes (p < 0.05) but only correlated with necrosis (IL-1α: r = 0.80; IL-1β: r = 0.77; p < 0.0001) in CF AEC." (PMID 32328066, 2020). "A cell death mechanism, known as pyroptosis, was shown to be important for controlling several infections by activating the inflammasome complexes and the subsequent secretion of the mature pro-inflammatory cytokines, interleukin 1β (IL-1β) and IL-18." (PMID 32013758, 2020). "We chose to a 1 hr infection because of a previous report that showed Toxoplasma-induced expression of key monocyte genes, including IL1β, occur as early as 1 hr post infection, followed by a gradual decrease in expression." (PMID 33273621, 2020). "We also found a direct correlation in both PTB in mice with ascending infection and significant relationship between UP presence and increased TNFα, IL-1β, CXCL-1 and CXCL-2 cytokine expression in foetal membranes, placenta and the myometrium." (PMID 31924800, 2020). "TNF, IL-1β, and IL-6 are important cytokines that mediate initial response of innate immune system to infections." (PMID 32133014, 2020). "Infection of Syrian hamsters with either Ad14 or Ad14p1 induced expression of IL-1β and TNF-α at day 1 post infection." (PMID 32486177, 2020). "We also measured an increase of IL-1β levels secreted at 4 h of infection, and the same pattern was repeated for TNF-α." (PMID 33253325, 2020). "IL-8 and IL-1b induce chemotaxis and play a key role in inflammation, recruiting neutrophils to the site of infection." (PMID 31940898, 2020). "All tested cytokines had lower levels in Gdf15−/− mice, which reached statistical significance in the cases of IL-1β and IL-12 suggesting better control of infection in Gdf15−/− mice." (PMID 32424099, 2020). "In the intestine, IL-23A is thought to act synergistically with IL-1β to promote pathogenic ILC and Th17 responses following infection with Helicobacter hepaticus." (PMID 31964744, 2020). "Results showed that the expression of IL-1β was significantly upregulated after 2 h infection (p < 0.01)." (PMID 32746898, 2020). "At 24 h post-infection, brains (hippocampus and cerebral cortex) were harvested to examine the expression of proinflammatory factors (Tnf-α, Il-1β, and Il-6) by RT-PCR." (PMID 32676082, 2020). "One of the fundamental reactions of the innate immune responses to pathogen infection is the release of pro-inflammatory cytokines, including IL-1β, processed by the NLRP3 inflammasome." (PMID 32187211, 2020). "To assess for a possible active inhibition of the inflammasome and IL-1β production in cells infected with M. tuberculosis isolate 6C4, we next performed mixed infections of BMDMs." (PMID 32327653, 2020). "STING has the essential roles in innate immune response against pathogen infections and is required for pathogen-induced inflammasome activation and IL-1β secretion." (PMID 32187211, 2020). "IL-1β is a strong pro-inflammatory cytokine that is critical for defense responses to infection and injury." (PMID 32370250, 2020). "RSV infection of SIRT1-/- BMDC induced significantly higher Il1β, Il6 and Il23 expression early in the infection as compared to WT+RSV." (PMID 32106265, 2020). "An interesting finding was that some mediators were more affected by TLR2 loss in the brain compared to the galea, including IL-1β, CCL2, TNF-α, IL-6, and CXCL2, which was particularly evident at day 14 post-infection." (PMID 32290861, 2020). "IL-1β, that increases upon infection but also during prenatal stress and maternal deprivation, appears to reduce the transporter expression, delaying the GABA switch and resulting in abnormal brain development." (PMID 33060559, 2020).
infection (continued). "In fact, the neutrophil numbers in animals treated with LPPIII increased significantly, coordinated with the release of IL-1β, that acted recruiting these cells, resulting in the reduction in bacteria numbers at the site of infection." (PMID 33237133, 2020). "TNF and IL-1β both activate endothelial cells and attract circulating polymorphonuclear white blood cells (PMNs) to the infection site." (PMID 32133014, 2020). "IL-1β protein levels in DF1 cells also increased gradually post GM infection, reaching the final peak (172.7 pg/mL) at 36 hpi." (PMID 32293543, 2020). "Infection with Klebsiella pneumoniae lead to significantly larger amounts of IL-1β release from both murine and human macrophages when compared to Staphylococcus aureus strains, in presence and absence of uric acid." (PMID 33322651, 2020). "The secretion of cytokines, mainly IL-6 and IL-1β, also promotes the recruitment of other immune cells, mainly monocytes and T lymphocytes, to the infection sites." (PMID 32781571, 2020). "It has been reported that in the activation of the defense mechanisms, the production of TNF-α, along with IL-1β and IL-6, induces a protective inflammatory response for infection control." (PMID 32423093, 2020). "In the in vivo model, with infection of mice, treatment with baicalein inhibited the growth of H. pylori in the stomach of these animals and the serum levels of IL-1β and IgM and IgA specific for H. pylori were reduced." (PMID 33233494, 2020). "Flaviviruses, including the West Nile virus, swine fever virus (CSFV), Japanese encephalitis virus, and hepatitis C virus, have been shown to assemble the NLRP3 inflammasome and promote IL-1β production during infection." (PMID 32210961, 2020). "There was a significant upregulation of pro-inflammatory cytokines, specifically IL-1β and IL-6, in challenged birds fed with normal starter formula (T2), at day 2 post-infection." (PMID 33260977, 2020). "Nonetheless, in vivo IFN-γ neutralization in IL-17RA KO mice (at days 3 and 6 post-infection) increased skin production of Th17-lineage cytokines (IL-22, IL-17, IL-1β, IL-6) and significantly inhibited fungal growth." (PMID 33343578, 2020). "In the spinal cord, WT-infected mice had higher levels of Il6, Tnf, Ccl2, and Ccl5 mRNAs at 2 or 4 days after infection, while Il1β was highest in Y114A at 2 and 6 days (P < 0.01 versus G32S, P < 0.0001 versus Y114A)." (PMID 32047134, 2020). "IL-1β is an upstream pro-inflammatory cytokine that is released following activation of the inflammasome in response to infection and/or injury." (PMID 32719685, 2020). "In epithelial cells, HSV-1 can induce the secretion of TNFα, IL-1β and other inflammatory factors, that is, the inflammatory response participates in the host’s resistance to pathogen infection." (PMID 33195272, 2020). "The level of IL-1β mRNA was significantly higher in the lungs of klotho KO mice than in those of klotho WT mice at 1 day post-infection." (PMID 33329595, 2020). "We next measured the production of IL-1β induced upon infection of cells from different origins with M. tuberculosis isolate 4I2 or 6C4." (PMID 32327653, 2020). "During infection, IL-1β is induced, and an increased expression of IL-1β has been reported in the intestine of different species, including gilthead seabream, after intraperitoneal challenge with gram negative bacteria." (PMID 33066515, 2020). "Upon prolong monitoring of IL-1β for 24 days post infection in these 3 focus groups where statistical significance in critical and severe patients was seen on 15th day." (PMID 33634060, 2020). "The result detected by ELISA in mice showed that the levels of TNF-α and IL-1β were increased in the LPS-treated group compared to the control group before infection." (PMID 33232366, 2020). "The number of dead cells, ASC specks and IL-1β secretion increased with increasing multiplicity of infection (MOI)." (PMID 32385301, 2020).